SYNE1 (spectrin repeat containing nuclear envelope protein 1)
Diseases named in the same sentence as SYNE1 in open-access papers (continued):
Sharing a sentence is not in itself a finding about the gene and the disease.
laminopathies (5 papers, 2015 to 2023). "Furthermore, SYNE1 has been reported to participate in laminopathies and lamin-associated signaling pathways, leading to laminopathies and premature aging." (PMID 33330489, 2020). "Dysregulation of genes involved in organizing and maintaining nuclear structures, such as SYNE1, SYNE2, TREM43, EMD and LMNA is frequently associated with diverse diseases termed laminopathies, which often affect the muscle tissue." (PMID 25906157, 2015). "Thus, mutations in SYNE1/2 that disrupt these specific nesprin-1 and -2 isoforms, or mutations in other components of the LINC complex that disrupt their binding with nesprin-1 and -2, are likely to play a key role in muscle-specific laminopathies." (PMID 28398466, 2017).
major depression (5 papers, 2012 to 2024). "Finally, correlations between mutations in SYNE1 with bipolar disorder or depression have been found." (PMID 28854936, 2017). "SYNE1 has an alternative splice form called CPG2 that functions in postsynaptic recycling of glutamate receptors, and has been subsequently associated with major depression." (PMID 23025490, 2012). "It has since been recognized that SYNE1 could be involved in schizophrenia, depression and autism." (PMID 28854936, 2017).
arthrogryposis (4 papers, 2016 to 2025). A rare, non-progressive congenital disorder characterized by multiple joint contractures which are present at birth. "Since the original report SYNE1 mutations have also been identified in families with motor neuronopathy and arthrogryposis but few families have been screened as the gene is very large at 146 exons in length." (PMID 27178001, 2016). "This may suggest that variants in SR61-SR63 of SYNE1 protein would increase the susceptibility to arthrogryposis." (PMID 30619065, 2018).
neuropathy (4 papers, 2020 to 2024). A disorder affecting the nervous system that manifests with pain, tingling, numbness, and/or muscle weakness. "At least TUBGCP6, SYNE1, BPTF, KIDINS220, MYO5A, VPS13B, TBC1D24) are known to contain mutations causing various neuropathies." (PMID 32561887, 2020). "In this case, while the neuropathy findings of the patient were compatible with the variant in the SYNE1 gene, the variant in the PRKCG gene could not be ruled out and it is thought to be effective on the phenotype." (PMID 38587696, 2024).
prostate carcinoma (4 papers, 2015 to 2024). A carcinoma that arises from epithelial cells of the prostate gland. "SYNE1 was the third most frequently mutated gene (16%) in the novel prostate cancer set." (PMID 36922933, 2022). "We identified ancestry-linked germline and somatic mutation frequencies in DNA damage repair genes (BRCA1, BRCA2, APC, and ATM), as well as three novel prostate cancer–associated genes (CACNA2D2, SYNE1, and ADAMTS2)." (PMID 36922933, 2022).
amyotrophic lateral sclerosis (3 papers, 2021 to 2024). Amyotrophic lateral sclerosis (ALS) is a neurodegenerative disease characterized by progressive muscular paralysis reflecting degeneration of motor neurons in the primary motor cortex, corticospinal tracts, brainstem and spinal cord. "Many case reports have been published, and one example shows that novel heterozygous mutations in the SYNE1 gene have also been reported in juvenile amyotrophic lateral sclerosis (ALS)." (PMID 38255218, 2024).
clear cell renal cell carcinoma (3 papers, 2020 to 2025). "Additionally, SYNE1 mutations in patients with clear cell renal cell carcinoma are involved in immune response signal and alterations based on the profiles of infiltrating immune cells." (PMID 34513706, 2021). "In the present study, we reported SYNE1 mutations associated with worse prognosis in patients with ESCC, which is consistent with a previous report of patients with clear cell renal cell carcinoma showing that SYNE1 mutations correlate with a higher tumor mutation burden and poorer outcomes." (PMID 34513706, 2021). "A recently published study suggested that SYNE1 mutation was associated with a higher TMB and a worse survival in clear cell renal cell carcinoma and may enhance the response to PD‐1/PD‐L1 blockade therapy." (PMID 40948427, 2025).
head and neck cancer (3 papers, 2017 to 2021). A primary or metastatic malignant neoplasm affecting the head and neck. "Of the other validated genes, only one has previously been associated with cytotoxic chemotherapy response in other cancers: somatic variants in SYNE1, which codes for a nuclear envelope-associated protein, correlated with poor response to induction chemotherapy in head and neck cancer." (PMID 32734521, 2020).
Intellectual disability (3 papers, 2015 to 2021). "SYNE2 variations may affect SYNE1 functions, which has already been associated with intellectual disability and ASD." (PMID 34573277, 2021). "Moreover, SYNE1 mutations may also contribute to intellectual disability, ALS, ASD and bipolar disease." (PMID 34573277, 2021). "Therefore, SYNE1 gene mutations could cause EDMD4 and spinocerebellar ataxia type 8 theoretically, as well as myogenic arthrogryposis multiplex congenita with EDMD features and intellectual disability with spastic paraplegia and axonal neuropathy." (PMID 28583108, 2017).
motor neuron disease (3 papers, 2016 to 2018). "For SYNE1, as mainly loss-of-function mutations are considered as being pathogenic in motor neuron disease." (PMID 27790088, 2016).
arthrogryposis multiplex congenita (2 papers, 2018 to 2021). Arthrogryposis multiplex congenita (AMC) is a group of disorders characterized by congenital limb contractures. "In addition, numerous recessive genetic psychiatric disorders have been associated with SYNE1 deficiency, comprising a phenotypic spectrum ranging from cerebellar ataxia to arthrogryposis multiplex congenita (AMC)." (PMID 34203885, 2021).
asthma (2 papers, 2016 to 2020). "The SYNE1 gene was recently associated with the pathogenesis of asthma." (PMID 32539833, 2020). "In addition, asthma, a known inflammatory disease, is known to worsen upon exposure to PM, and one gene, SYNE1, has been suggested to have a role in asthma attacks." (PMID 32539833, 2020). "Thus, SYNE1 could potentially have an effect on airway smooth muscle and influence muscle function during asthma attacks." (PMID 27445529, 2016). "This study also suggests a potential role for new loci, namely, SYNE1, LINGO2, and IFNG-AS1, in the pathogenesis of asthma." (PMID 27445529, 2016).
autism spectrum disorder (2 papers, 2022 to 2024). A spectrum of developmental disorders that includes autism, and Asperger syndrome. "Both SYNE1 and TGM3 have been highlighted in a study of de novo mutations in autism spectrum disorder." (PMID 36457050, 2022).
autosomal recessive spinocerebellar ataxia (2 papers, 2014 to 2024). "We report a case of SYNE1-associated autosomal recessive spinocerebellar ataxia (SCAR8) presenting with a complex multisystemic phenotype, including highly elevated creatine kinase levels and lower-leg muscle atrophy." (PMID 39409170, 2024).
congenital muscular dystrophy (2 papers, 2017 to 2023). A muscular dystrophy that is characterized by diminished muscle tone (hypotonia), progressive muscle weakness and degeneration (atrophy), abnormally fixed joints, spinal rigidity, and delays in reaching motor milestones such as sitting or standing unassisted. "Furthermore, we demonstrate that this mechanism is disrupted in congenital muscular dystrophy patient myotubes carrying a nonsense mutation within the SYNE1 gene (23560 G>T) encoding Nesprin-1." (PMID 28966089, 2017).
COVID-19 (2 papers, 2021 to 2024). A disease caused by infection with severe acute respiratory syndrome coronavirus 2. "An additional 8 targets (CXCL6, IFI44, IFI44L, RSAD2, S100A8, SPRR2A, SYNE1, XAF1) are associated with COVID-19 pathogenesis, but do not have therapies targeting them available for potential repurposing." (PMID 34582497, 2021).
epilepsy (2 papers, 2021 to 2024). A brain disorder characterized by episodes of abnormally increased neuronal discharge resulting in transient episodes of sensory or motor neurological dysfunction, or psychic dysfunction. "Our findings demonstrate that pilocarpine-induced epilepsy profoundly increases the number of circadian cilia-associated genes in the hippocampus, with a notable rise in 24 Syne1 isoforms exhibiting circadian patterns in the epileptic state compared to 12 in the control." (PMID 39304885, 2024).
hypercholesterolaemia (2 papers, 2020 to 2025). "There are also available data indicating a possible role of SYNE1 variants (although others than those shown in our study) in the development of CAD by their involvement in the morbidity of hypercholesterolemia and hypertriglyceridemia through gene–gene and SNP-SNP interactions." (PMID 40076866, 2025).
leiomyoma (2 papers, 2018 to 2021). A well-circumscribed benign smooth muscle neoplasm characterized by the presence of spindle cells with cigar-shaped nuclei, interlacing fascicles, and a whorled pattern. "A previous report demonstrated that a long segment (over 500,000 bp) within SYNE1 was identified, manifesting a high acetylation status in chromatin and possibly playing a crucial role in modulation of the expression of SYNE1 and/or other adjacent genes in leiomyoma." (PMID 34944636, 2021).
leukemia (2 papers, 2021 to 2024). A malignant (clonal) hematologic disorder, involving hematopoietic stem cells and characterized by the presence of primitive or atypical myeloid or lymphoid cells in the bone marrow and the blood. "Of the upregulated genes, Syne1, Atxn10 and Dach1 show activation as early as Day 11, while Ngp, Abca13, Adpgk, Mmp8 and Lcn2 were more significantly upregulated in the later stage, D14 neutrophils,which suggests a sequential activation in Camk1d + neutrophils during leukemia progression." (PMID 38730491, 2024). "Excluding the SYNE1, NOTCH4, and CHEK1 genes, all others are well known leukemia/lymphoma cancer genes with a tier 1 category in the Cancer Gene Census database." (PMID 34573308, 2021).
lung adenocarcinoma (2 papers, 2018). A carcinoma that arises from the lung and is characterized by the presence of malignant glandular epithelial cells. "On the other hand, USH2A, LRP1B, MUC16, and SYNE1 genes have been reported to have frequently mutated in various cancer types, particularly lung adenocarcinoma and lung squamous cell carcinoma." (PMID 30555633, 2018).
myocardial infarction (2 papers, 2015 to 2025). Gross necrosis of the myocardium, as a result of interruption of the blood supply to the area, as in coronary thrombosis. "In conclusion, a novel variant of the SYNE1 gene is associated with myocardial infarction in patients of a young age with a family history of premature atherosclerosis." (PMID 40076866, 2025).
myogenic arthrogryposis multiplex congenita type 3 (2 papers, 2022). "An enlargement of the perinuclear space has furthermore been reported in myogenic-type arthrogryposis multiplex congenita-3 (AMC3) patients harboring SYNE1 mutations." (PMID 35810298, 2022). "Considering the homozygous variant in the SYNE1 gene and the matching clinical picture of the patient, the patient was diagnosed as myogenic arthrogryposis multiplex congenita type 3." (PMID 35739559, 2022).
spinocerebellar ataxia type 8 (2 papers, 2017 to 2024). Spinocerebellar ataxia type 8 (SCA8) is a subtype of type I autosomal dominant cerebellar ataxia (ADCA type I) characterized by cerebellar ataxia and cognitive dysfunction in almost three quarters of patients and pyramidal and sensory signs in approximately a third of patients. "Based on the clinical phenotype, the biparental inheritance of both SYNE1 variants, and the altered splicing as revealed by the RNA studies, the patient received the diagnosis of spinocerebellar ataxia type 8 (SCAR8, OMIM: 610743)." (PMID 39669622, 2024).
transitional cell carcinoma (2 papers, 2021 to 2022). A malignant neoplasm arising from the transitional epithelium, usually affecting the urinary bladder, ureter, or renal pelvis. "Mutation of SYNE1 in exonic rs9479297 leads to the upregulation of proteins SYNE1, which may contribute to cell proliferation and migration in hepatocellular and transitional cell carcinoma." (PMID 35975176, 2022).
triple-negative breast carcinoma (2 papers, 2021 to 2024). An invasive breast carcinoma which is negative for expression of estrogen receptor (ER), progesterone receptor (PR), and human epidermal growth factor receptor 2 (HER2).
autosomal dominant Emery-Dreifuss muscular dystrophy (1 paper, 2016). Autosomal dominant form of Emery-Dreifuss muscular dystrophy. "Missense mutations in the 3’-region of SYNE1 usually result in autosomal-dominant Emery-Dreifuss muscular dystrophy or inherited cardiomyopathy, with nesprin-1 function impaired, though perhaps not abolished." (PMID 27350129, 2016).
blepharospasm (1 paper, 2023). "Only two patients had a family history of blepharospasm; mutations in SYNE1 and CIZ1 were detected in these patients, suggesting that mutations in SYNE1 and CIZ1 are the main genetic factors contributing to blepharospasm in these families." (PMID 38274886, 2023).
breast invasive carcinoma (1 paper, 2024). "The pathway describing the role of SYNE1 (Spectrin Repeat Containing Nuclear Envelope Protein 1) in the progression of breast invasive carcinoma has been proposed with the help of our bioinformatics analysis and detailed literature survey." (PMID 38977697, 2024).
cardiac hypertrophy (1 paper, 2025). "SYNE1 has been shown also to be involved in angiotensin-II-induced cardiac hypertrophy by the miR-525-5p/specific protein transcription factor SP1 axis." (PMID 40076866, 2025).
colitis (1 paper, 2016). Inflammation of the colon. "Moreover, it has recently been suggested that detecting methylation of FOXE1 and SYNE1 genes in colitis-associated colorectal neoplasia could be a promising biomarker." (PMID 27517910, 2016).
diabetic nephropathy (1 paper, 2023). "Finally, both SYNE1 and MYO1B have been described as related to diabetic nephropathy before." (PMID 36769128, 2023).
gynecological cancer (1 paper, 2020). "Furthermore, TTN, MUC16, CSDM3, RYR2, USH2A, and SYNE1 were frequently mutated in gynecological cancers but not in the MSK-IMPACT samples, suggesting that they play specific roles in the development of gynecological malignancies." (PMID 32626534, 2020).
hereditary ataxia (1 paper, 2021). An instance of an atactic disorder that is caused by an inherited genomic modification in an individual. "SACS and SYNE1 mutations have been observed mainly in Quebec and Canada, where ARSACS and SCAR8 are the second and third most common hereditary ataxia, respectively." (PMID 34663476, 2021).
Hypertension (1 paper, 2024). The presence of chronic increased pressure in the systemic arterial system. "SYNE1 is highly expressed in cardiac, skeletal, and vascular smooth muscle tissues, and common variants near SYNE1 have been associated with pulse pressure and mean arterial pressure in 2 large GWAS of hypertension." (PMID 38716726, 2024). "Notably, SYNE1 was also among our priority list of 1,310 genes implicated in hypertension." (PMID 38716726, 2024). "Here we report genetic, physiological, and biophysical experimental evidence supporting the contention of a role for SYNE1 in the development of early-onset hypertension." (PMID 38716726, 2024). "We hypothesized that recessive inheritance of a putatively damaging variation might lead to reduced functionality of the resulting SYNE1 protein, Nesprin-1, which could affect vascular stiffness and lead to hypertension." (PMID 38716726, 2024). "Finally, we provide biophysical experimental support for the functional role of reduced SYNE1 in the vascular stiffness phenotype seen in hypertension." (PMID 38716726, 2024). "The likely damaging nature of these variants paired with the observed effect of SYNE1 KD in vascular in vitro models suggests that aberrant production of SYNE1 may ultimately lead to increased total peripheral resistance and subsequently hypertension." (PMID 38716726, 2024).
leukoplakia (1 paper, 2025). A white patch or plaque on a mucous membrane that cannot be characterized clinically or pathologically as any other disease. "Therefore, downregulation results in elevated expression of CD44v6 and reduced SYNE1, both in patients with leukoplakia and OSCC." (PMID 41303164, 2025).
migraine (1 paper, 2014). "SNPs rs3093664 (TNF) and rs9371601 (SYNE1) were both significantly associated with migraine in the combined PMM-MRM sample and the MRM sample." (PMID 25315199, 2014). "SNPs rs3093664 and rs9371601 in TNF and SYNE1 genes respectively, were significantly associated with migraine in the MM population (p = 0.008; p = 0.009 respectively)." (PMID 25315199, 2014). "In this research, we have identified significant differences between MM cases and controls, which both show increased risk of migraine development for the G alleles in the tested SNPs in the TNF and SYNE1 genes." (PMID 25315199, 2014). "This study was aimed at investigating genetic variants that are potentially related to MM, specifically undertaking genotyping and mRNA expression analysis of the ESR1, PGR, SYNE1 and TNF genes in MM cases and non-migraine controls." (PMID 25315199, 2014).
myeloma (1 paper, 2025). "Recurrent lymphoid CH mutations (in FAT1, KMT2D, MGA, and SYNE1) and myeloma driver gene mutations (in ZFHX3 and DIS3) were found in the dominant clonal and subclonal plasma cell populations." (PMID 40152254, 2025). "Despite the distinct burden of subclonal mutations, some CH mutations were conservative among MM, AL, POEMS, and MGUS, including lymphoid and myeloid CH mutations, such as those in KMT2D, FAT1, MGA, and SYNE1, and myeloma driver genes like ZFHX3 and DIS3." (PMID 40152254, 2025).
myofibrillar myopathy (1 paper, 2021). "It is of note that the SYNE1 intronic variants putatively affecting the clinical phenotype of patients with myofibrillar myopathy were recently identified by us." (PMID 34203885, 2021).
neuromuscular junction disease (1 paper, 2018). Conditions characterized by impaired transmission of impulses at the neuromuscular junction. "Finally, some emerging role of nesprin-1 in the formation of striated F-actin-based filaments or in Drosophila, in the control of glutamate receptors density, specifically at the neuromuscular junction suggests that SYNE1 mutations could be highlighted in other neuromuscular junction diseases." (PMID 30245638, 2018).
osteoporosis (1 paper, 2024). A condition of reduced bone mass, with decreased cortical thickness and a decrease in the number and size of the trabeculae of cancellous bone (but normal chemical composition), resulting in increased fracture incidence. "This highlights the lncRNA NONMMUT004552.2/miR-15b-5p/Syne1 axis as a therapeutic target during osteoporosis." (PMID 38521778, 2024).
rectal tumors (1 paper, 2025).